IKZF5 (IKAROS family zinc finger 5)
Description:
Transcriptional repressor that binds the core 5'GNNTGTNG-3' DNA consensus sequence. Involved in megakaryocyte differentiation.
Synonyms: ZNFN1A5; Pegasus; FLJ22973; THC7
Tractability: Antibody: the Human Protein Atlas places it where antibodies can reach. PROTAC: UniProt records ubiquitination sites on it; ubiquitination databases record sites on it; its protein half-life has been measured.
Gene: Protein-coding gene on chromosome 10 (122,990,806 to 123,008,826, reverse strand). Ensembl gene ENSG00000095574.
Subcellular location: Nucleus
Subcellular location (Human Protein Atlas): Nucleoplasm; Cytosol; Plasma membrane
Gene Ontology:
Molecular function: chromatin binding; DNA-binding transcription repressor activity, RNA polymerase II-specific; protein binding; protein domain specific binding; RNA polymerase II transcription regulatory region sequence-specific DNA binding; zinc ion binding; DNA-binding transcription factor activity; RNA polymerase II cis-regulatory region sequence-specific DNA binding
Biological process: negative regulation of transcription by RNA polymerase II; regulation of transcription by RNA polymerase II
Cellular component: nucleoplasm; nucleus; protein-containing complex
Genetic constraint (gnomAD): Loss-of-function variants: 4 observed, 32.03 expected, observed/expected ratio (o/e) 0.12, 90% interval 0.061 to 0.29. The synonymous counts are far from expectation, so gnomAD's model fits this gene poorly and the ratio says little. Missense variants: 343 observed, 550.3 expected, observed/expected ratio (o/e) 0.62, 90% interval 0.57 to 0.68. Synonymous variants: 147 observed, 188.35 expected, observed/expected ratio (o/e) 0.78, 90% interval 0.68 to 0.89.
Gene-disease validity (ClinGen):
ClinGen rates the evidence that IKZF5 causes each of these diseases.
thrombocytopenia 7 (autosomal dominant): Moderate.
Homologues: Orthologues: macaque IKZF5 (100% identical), chimpanzee IKZF5 (99% identical), dog IKZF5 (99% identical), pig IKZF5 (99% identical), rat Ikzf5 (99% identical), mouse Ikzf5 (97% identical), tropical clawed frog ikzf5 (87% identical), zebrafish ikzf5 (68% identical). Paralogues in human: ZFAT (21% identical), ZFX (20% identical), ZFY (20% identical), ZNF711 (19% identical), PRDM15 (17% identical), E4F1 (16% identical), ZBTB11 (16% identical), ZNF551 (16% identical), ZSCAN2 (15% identical), ZNF304 (14% identical), ZNF583 (14% identical), ZSCAN20 (14% identical), and 26 more.
Diseases named in the same sentence as IKZF5 in open-access papers:
IKZF5 is named in the same sentence as 7 diseases in open-access papers, as found by Europe PMC text mining. Sharing a sentence is not in itself a finding about the gene and the disease. The quoted sentences say what the papers report.
cancer (1 paper, 2022). A tumor composed of atypical neoplastic, often pleomorphic cells that invade other tissues. "The Pearson coefficient index of every pair of Ikaros genes indicated that IKZF1 and IKZF3 were closely associated in various cancers, while IKZF3 and IKZF5 showed the weakest correlations." (PMID 36353107, 2022).
tumor (1 paper, 2022). "IKZF2 and IKZF5 were downregulated in the primary tumor, and IKZF1–3 expression decreased significantly as the T-stage or metastasis increased in SKCM." (PMID 36353107, 2022). "Moreover, among different tumor locations, Ikaros genes were expressed at the highest levels in regional lymph nodes, IKZF1 and IKZF3 were expressed at the lowest levels in distant metastases, and IKZF2, IKZF4, and IKZF5 were expressed at the lowest levels in the primary tumor." (PMID 36353107, 2022).
IKZF5 also shares sentences with these, for which no sentence is quoted: B cell lymphopenia (1 paper); combined immunodeficiency (1); common variable immunodeficiency (1); Pneumocystis jirovecii pneumonia (1); Thrombocytopenia (1).